KRAS (KRas proto-oncogene, GTPase)
Diseases named in the same sentence as KRAS in open-access papers (continued):
Sharing a sentence is not in itself a finding about the gene and the disease.
tumor (continued). "The discrepancies among the studies on the expression of let-7 miRNAs in CRC could be due to the different characteristics of tumoral tissues in terms of the grade, stage, tumor locations, presence of perineural invasion, and KRAS or BRAF mutation status." (PMID 36295073, 2022). "KRAS mutation was related to the depth of tumor invasion and clinical manifestations." (PMID 35837115, 2022). "Since KRAS mutations can lead to impaired mitochondrial respiration, this sophisticated reciprocal signaling node restores mitochondrial respiration in KRAS mutant tumor cells via SHH, IGF1R/AXL, and AKT." (PMID 36612058, 2022). "However, the signaling pattern specific for each KRAS mutant is affected by the tumor tissue of origin and by the coexisting mutations and other molecular alterations, preventing a simple predictive algorithm." (PMID 36358725, 2022). "Similarly, KRAS mutation reduces tumor immunogenicity by inhibiting tumor neoantigen accumulation, thereby promoting tumor progression." (PMID 35401671, 2022). "The clinical data metrics that showed statistically significant associations to the HDSCA data were KRAS mutation status, location of tumor in colon, tumor stage, size of metastasis, location of metastasis, synchronous disease status, and if the patient had received neoadjuvant chemotherapy." (PMID 35158910, 2022). "Six out of seven patients expressed a KRAS mutation in tumor tissue." (PMID 35448266, 2022). "Co-alteration landscapes were largely similar across KRAS mutations but distinct from KRAS wild-type, though differences were observed in some tumor types for tumor mutational burden, PD-L1 expression, microsatellite instability, and other mutational signatures." (PMID 36494601, 2022). "In addition to being the most frequently mutated oncogene in PDAC, gene dosage increases of mutant KRAS are already prevalent at early stages of tumour formation, and also drive metastatic dissemination in both mouse and human." (PMID 36088504, 2022). "Therefore, KRAS mutation is positively correlated with the curative effect of ICIs in cancer patients, but KRAS-G12C mutation is correlated with the shorter tumor recurrence time in early NSCLC patients." (PMID 36189266, 2022). "KRAS mutations can interact with the IL-22 pathway and enhance tumor cell proliferation." (PMID 36452508, 2022). "Interestingly, mounting evidence indicates that oncogenic KRAS mutations in cancer cells shape tumor microenvironment composition and affect the properties and functions of its constituents." (PMID 35719951, 2022). "We found that tumors with high-grade tumor budding had significantly more KRAS mutations." (PMID 35096426, 2022). "Moreover, down-regulation or loss of SOS1 lead to a decrease in the survival rate of tumor cells carrying KRAS mutations." (PMID 36139627, 2022). "TGFβ provided by tumor associated macrophages (TAMs) is the key driver of the KRAS bypass." (PMID 35966590, 2022). "Finally, taking for granted the prognostic significance of tumor mutational status, KRAS and BRAF mutations were correlated with TLR9—T1237C, TLR9—T1486C polymorphisms, and TLR9—T1486C, respectively." (PMID 36139567, 2022). "In addition to small molecule drugs directly targeting KRAS, other innovative therapeutic modalities for KRAS, such as RNA Interference (RNAi) therapies and KRAS-associated tumor vaccines, are also being extensively explored." (PMID 36118526, 2022).
tumor (continued). "Interestingly, mutations in KRAS were more frequently occurred in PEAC than other three tumor types." (PMID 35172862, 2022). "This information may have significant impact on the operation of clinical trials for rare tumor patients with KRAS mutations in China." (PMID 35359599, 2022). "Importantly, nanocomplex targeting of mutated KRAS in cancer cells can effectively inhibit tumor growth and metastasis in tumor-bearing mouse models." (PMID 35189910, 2022). "Our study demonstrates that MHC-I peptides derived from covalently modified intracellular proteins provide an unique source of tumor-specific neoantigens which require presence of a somatic KRAS G12C mutation and its modification by a covalent KRAS G12C specific drug." (PMID 36099883, 2022). "A comparison between the KRAS mutation status of the tumor material excised during surgery and the postoperative ctDNA in this patient cohort may aid in further elucidating the underlying mechanism governing the shift from mutation negative to positive." (PMID 35454933, 2022). "This approach makes our method also sensitive to RAS active tumours driven by non-KRAS mutations." (PMID 36163168, 2022). "In contrast, the KRAS-mut interactome is both smaller and has fewer conserved genes suggesting KRAS-mut cancers must compensate for limited oncogenic signal propagation through an increased number of additional tumor-promoting mutations." (PMID 36612014, 2022). "Furthermore, inhibition of SLC7A11 via genetic or pharmacological targeting attenuates mutant-KRAS associated tumor growth in xenograft models via induction of lipid peroxidation and ferroptosis." (PMID 35280777, 2022). "Thus, the LS location of the primary tumor was associated with significantly better OS rates after hepatectomy for CLMs only in KRAS-wt tumors, while in patients with KRAS-mut CLMs there was not any significant difference in OS according to the PTL." (PMID 36013567, 2022). "Similarly, in our observation for the tumor mutation burden, we clearly found the mutation rate of the KRAS gene gets higher in the group with high score risk." (PMID 35578598, 2022). "Four patients (15.4%) exhibited a KRAS variant both in their plasma and their tumor." (PMID 36551569, 2022). "In all cases, we found in the tumor tissue the same KRAS variant identified in the cfDNA." (PMID 36010306, 2022). "As recently reported by Zhao and colleagues, patients with a lower plasma KRAS c34G > T (pG12C) allele frequency and a lower tumor burden at baseline tend to be what are called exceptional responders (i.e., complete or partial response lasting more than 12 months) when treated with sotorasib." (PMID 36077640, 2022). "KRAS mutation is related to the depth of tumor invasion and the prognosis of ECRC." (PMID 35837115, 2022). "However, the coexistence of EGFR and KRAS mutations has been demonstrated in rare cases by tumor tissue testing, thus excluding that this phenomenon is only related to CHIP." (PMID 36010306, 2022). "- Phase 1- Sotorasib in patients with advanced tumours harbouring KRAS G12C mutations." (PMID 35251972, 2022). "Thus, inhibitors interfere with positive feedback regulation, which potentiates its GEF function, consequently reducing the survival of tumor cells with KRAS mutation." (PMID 34830024, 2021). "First, tumor cells harboring KRAS or NF-κB mutations release mitogenic and fibrogenic factors that can reprogram normal pro-fibrotic cells into active TAFs, including vascular endothelial growth factor (VEGF), platelet-derived growth factor (PDGF), TGF-β, and sonic hedgehog (SHH)." (PMID 34138315, 2021).
tumor (continued). "Furthermore, antigenic discontinuum owing to the oncogenic mutations (including those in KRAS) or chromosome rearrangements (such as BCR-ABL1) can induce a non-destructive immune response that is aberrantly considered as tumor immunity." (PMID 34138315, 2021). "We asked whether Braf is essential for KRAS-induced tumor growth and whether its loss affects tumor-immune interactions." (PMID 33674596, 2021). "For the subgroup of patients who carried a KRAS mutation and were treated with bevacizumab and doublet or triplet chemotherapy (N = 156), pretreatment circulating tumor DNA levels were analyzed, and total tumor volume (TTV) was quantified on the pretreatment computed tomography images." (PMID 34820593, 2021). "KRAS-mutated cancers express high levels of TRAIL with the ability to promote tumor growth." (PMID 33791337, 2021). "In addition to the microsatellite status (MSS), the epithelial mesenchymal transition was checked in each tumor using the biomarkers β-catenin and E-cadherin, same as KRAS and BRAF mutations." (PMID 33671994, 2021). "Additionally, the same mechanism has been reported by Lal and colleagues in RAS mutant CRC cells, where KRAS mutations were shown to strongly impact tumor immune infiltration compared to KRASWT samples." (PMID 33691728, 2021). "Besides, all the three subtypes of KRAS‐mutated tumor samples decreased significantly (p < 0.0001, Wilcoxon rank‐sum paired test)." (PMID 34076361, 2021). "It was also unable to compare the prognostic performance of vascular-metabolic profiles to well-known pathological risk factors such as tumour regression score, circumferential resection margin, lymphovascular/perineural invasion, microsatellite instability, KRAS, NRAS, BRAF mutations." (PMID 33837843, 2021). "Although lanperisone can effectively enhance ROS production mediated by the RAS/MEK/ERK signaling pathway to induce ferroptosis due to KRAS gene mutation in embryonic fibroblasts, it displays less competency than erastin in resisting against KRAS-driven tumor vitality." (PMID 34926476, 2021). "Biologic tumor characteristics differ on the basis of the KRAS mutation variant." (PMID 34820593, 2021). "Therefore, assessing the KRAS mutational status of tumor cells has become an essential tool for managing patients with CRC." (PMID 34811396, 2021). "However, in spite of these huge efforts, tumors carrying KRAS mutations remain among the most difficult to treat, largely because of development of drug resistance due to tumor cell plasticity and/or acquisition of new mutations." (PMID 34257283, 2021). "The percentage of patients with a KRAS A146–mutated tumor might be even higher than depicted in this study because routine molecular diagnostics is sometimes limited to the most common KRAS driver mutations, that is, the G12 and G13 variants." (PMID 34820593, 2021). "SHP2 plays an indispensable role in KRAS mutation-driven tumours." (PMID 34012925, 2021). "It will allow refined analyses using distributions of margin substrata as opposed to a simple “minimal ablation margin”, a correlation of QAM with regard to ASR in 3D space, as well as interactions between QAM and other factors known to affect ASR such as tumor diameter or KRAS mutational status." (PMID 33777768, 2021). "Notably, the KRAS gene frequently mutates in other cancers, such as pancreatic and lung, and is associated with poor prognosis, increased tumor aggressiveness and metastasis, and resistance to chemotherapy and targeted therapies." (PMID 34955846, 2021).
tumor (continued). "KRAS mutant CRC cells have been reported that it could promote tumour progression and induce resistance to cetuximab therapy; however, there is no effective treatment to specifically treat cancers expressing KRAS mutations." (PMID 34775496, 2021). "In addition, some CMS-associated characteristics such as MSI status, BRAFV600E, and KRAS mutations, as well as primary tumor location, are associated with different patterns of metastatic spread." (PMID 34262039, 2021). "In case 6, only metastasis was available for molecular testing but the detailed molecular report of his primary NSCLC could be retrieved; we detected the same KRAS mutation (reported in his primary tumor) in the intestinal metastasis." (PMID 33506327, 2021). "ARS-1620 achieves anti-tumor activity in subcutaneous xenograft models bearing KRAS G12C mutation." (PMID 34830757, 2021). "In NSCLC and colorectal cancers (CRC), the KRas mutation has been linked to an increased expression in PD-L1, an immune checkpoint protein expressed in tumor cells that interacts with the PL1 receptor on T-cells as a method of avoiding immune-mediated cell death." (PMID 34680208, 2021). "Indeed, in metastatic CRC (mCRC) metformin, accumulating in KRAS-mutated tumor cells inhibited tumor growth and cell viability." (PMID 34074330, 2021). "Her tumor was initially characterized as KRAS WT with several different variants of unknown significance (VUS)." (PMID 34504655, 2021). "Therefore, identical variants present in the genomic DNA of tumor cells, such as mutations in KRAS, NRAS, BRAF, and other genes, can be identified in ctDNA." (PMID 33919272, 2021). "Although the KRAS mutation activates the progrowth signaling pathway, recent studies have indicated that the KRAS mutation contributes to immune suppression for the evasion of tumor cells from the host immune response." (PMID 34272423, 2021). "Hallmarks of EMT and the “hypoxia” pathway enriched in the high-risk group promote tumor development and metastasis, and “G2M checkpoint”-related gene overexpression and deficiency of KRAS inhibition-related genes promote abnormal cell division in different tumors." (PMID 35273966, 2021). "A similar approach for KRAS mutations has been described in other tumor types." (PMID 33673558, 2021). "KRAS is the most frequently mutated RAS family member that can potentiate tumor-promoting activity." (PMID 34744708, 2021). "KRAS G12C allele inhibitors trap oncoproteins in an inactive state by inhibiting the reactivation of exchanged nucleotides, thereby blocking the proliferation of tumour cells that depend on the protein’s signalling pathways." (PMID 34012925, 2021). "In addition, GC1118 is a novel, fully humanized anti-EGFR IgG1 antibody that displays inhibitory effects against patient-derived xenografts from CRC tumours with a KRAS mutation, especially in those with elevated expression of high-affinity ligands." (PMID 34663410, 2021). "Interestingly, this tumor had a KRAS-G12C mutation, thus reinforcing the notion that aggressive primary tumors graft preferentially and suggesting tumor evolution during the passages." (PMID 34198671, 2021). "Although our knowledge about the molecular background of AOT is still very limited, the genetic data collected by this review points to the direction that AOT harbor mutations in important oncogenic driver genes, such as KRAS, and based purely on this, some authors have proposed it as a neoplasm." (PMID 35048068, 2021). "We show that this reduction in tumor growth was, as in 2D- and 3D-transformed growth assays, associated with a reduction in oncogenic KRAS signaling, namely we observed a reduction in P-ERK and P-AKT levels in tumors in which EFR3A, EFR3B, or both genes were inactivated." (PMID 34504076, 2021).
tumor (continued). "KRAS non-Exon2 mutations were more common in the primary tumor of the left colon." (PMID 33962575, 2021). "Indeed, a KRAS mutation observed from a primary tumor is one of the most widely studied chromosomal instabilities for CRC." (PMID 34442609, 2021). "The authors demonstrated differential expression levels of ACTA2 (CAFs marker) among tumors with different KRAS mutation status suggesting that CAFs may play a role in selecting tumor cells with specific driver mutations." (PMID 33691728, 2021). "In the present this study, having excluded the presence of mutations in EGFR or KRAS by highly specific and sensitive techniques in the primary tumor, we are able to confirm that the mutations detected in other lung cells were not the result of contamination from the tumor." (PMID 34257550, 2021). "Thus, we provide evidence that not only do the biological properties of the KRAS alleles contribute to their effect on the tumor, but so too do their unique genetic interactions." (PMID 33753749, 2021). "We screened 275 PDAC patient tumour biopsies for the presence of KRAS mutations." (PMID 34956889, 2021). "The sample size is based on the innovative hypothesis that radiation-induced immunity could induce regression of tumor clones bearing KRAS oncogene mutations." (PMID 34439390, 2021). "In conclusion, immune checkpoint inhibitors could be a recommendation for NSCLC patients having EGFR wild-type, KRAS mutation, and PD-L1 tumor proportion scores >1%." (PMID 33725808, 2021). "KRAS mutations occur in up to 95% of cases and render the tumor resistant to many types of therapy." (PMID 33807330, 2021). "Apart from the conventional pathway that is typically initiated by characteristic APC mutation and chromosomal instability, the serrated neoplasia pathway is mainly characterized by mutations of BRAF or KRAS, microsatellite instability (MSI), and CpG island methylator phenotype (CIMP)." (PMID 33382354, 2021). "Interestingly, the KRAS mutation in both tumors were distinct, suggesting that KRAS is needed for tumor development but is independent and likely secondary to PALLD alterations." (PMID 33764904, 2021). "Also, patients with the less common KRAS K117 mutation progressed faster, whereas patients with a tumor with a mutation in KRAS G13 had the most favorable prognosis." (PMID 34820593, 2021). "It has been suggested that distinct carcinogens may act differently to cause specific KRAS mutations and create selective pressures that will guide the process of tumor initiation in each tissue type." (PMID 33632153, 2021). "However, mutations are also commonly present in KRAS Q61 (2%), K117 (1%), and A146 (4%).4,5,14 Here, we investigated clinical features like tumor load and overall survival of patients with mCRC with a somatic mutation in KRAS G12, G13, Q61, K117, or A146." (PMID 34820593, 2021). "We, therefore, tested whether KRAS mutation in tumor cells has a role in the functional reprogramming of TAMs." (PMID 33833221, 2021). "Deletion of EGFR suppressed mutant KRAS activity and caused tumor growth temporarily." (PMID 34200786, 2021). "Current research evidence suggests a significant influence of KRAS mutation in tumor immunity." (PMID 33413474, 2021). "Does the tumor have mutations in other KRAS alleles due to the heterogeneity of CRC?" (PMID 34742312, 2021). "Interestingly, KRAS mutations are increasingly shown to affect tumor interactions with the surrounding TME." (PMID 33494181, 2021). "Interestingly, all of the KRAS variants from both tumor types were located at the same position, a known hotspot (p.G12V)." (PMID 34944094, 2021). "KRAS mutation results in highly invasive tumor biology and poor prognosis." (PMID 34692541, 2021).